ZHX1-C8orf76 (ZHX1-C8orf76 readthrough)
Tractability: PROTAC: ubiquitination databases record sites on it.
Gene: Protein-coding gene on chromosome 8 (123,226,189 to 123,274,284, reverse strand). Ensembl gene ENSG00000259305.
Subcellular location (Human Protein Atlas): Nucleoplasm; Cytosol
Gene Ontology:
Molecular function: protein binding
Genetic constraint (gnomAD): Loss-of-function variants: 30 observed, 29.75 expected, observed/expected ratio (o/e) 1.01, 90% interval 0.75 to 1.37. The upper end of that interval is the gene's LOEUF score, 1.37, which puts it in group 5 of 6, group 1 being the genes least tolerant of losing a copy. Missense variants: 318 observed, 338.3 expected, observed/expected ratio (o/e) 0.94, 90% interval 0.86 to 1.03. Synonymous variants: 122 observed, 127.42 expected, observed/expected ratio (o/e) 0.96, 90% interval 0.83 to 1.11.